PTH (parathyroid hormone)
Diseases named in the same sentence as PTH in open-access papers (continued):
Sharing a sentence is not in itself a finding about the gene and the disease.
hyperphosphatemia (continued). "Additionally, after the transplantation, suboptimal graft function, immunosuppressive drugs, metabolic acidosis, hyperphosphataemia, and low vitamin D levels also may increase PTH secretion and contribute to persistent HPT." (PMID 36672533, 2022). "Therefore this remaining proportion of iFGF23 could collectively reflect additional stimulators of FGF23 in CKD, such as hyperphosphatemia, inflammation, and PTH among others." (PMID 32476270, 2020). "In addition to the reduction in CrC, our data reproduced the kinetics of both early and late biochemical indicators of CKD MBD; early biochemical markers included a rise in FeP and FGF-23 levels, with elevation of PTH levels and hyperphosphatemia as late markers." (PMID 31419270, 2020). "Thus, in the presence of hyperphosphatemia, more PTH is required to maintain serum Ca levels." (PMID 32913635, 2020). "Patients with persistently high PTH levels (PTH > 800 pg/mL for longer than sixmonths) despite adequate drug therapy (maximum tolerated dose of vitamin D analoguesand calcimimetics combined) often accompanied by hyperphosphatemia and/orhypercalcemia meet the criteria for parathyroidectomy." (PMID 31419274, 2019). "The hypothesis explains why [PTH] fell with IP while hyperphosphatemia persisted." (PMID 28445401, 2017). "Additionally high PTH level increases bone efflux of P that contributes to hyperphosphatemia." (PMID 26808154, 2016). "PTH and FGF-23 cannot do their phosphaturic effects, resulting in hyperphosphatemia due to further elevations in iPTH and FGF-23." (PMID 40612843, 2025). "Even before the development of overt hyperphosphatemia, phosphorus dietary phosphorus load in CKD leads to an increase in FGF-23 and PTH, key factors driving the development of CKD-MBD." (PMID 40362897, 2025). "PHPT typically presents with hypophosphatemia (<2.5 mg/dL) due to PTH-induced phosphaturia, while SHPT patients often have hyperphosphatemia (>2.0 mmol/L)." (PMID 41227247, 2025). "In CKD, reduced glomerular filtration of phosphate is initially counteracted by the phosphaturic hormones fibroblast growth factor 23 (FGF23) and parathyroid hormone (PTH), before these compensatory mechanisms are overwhelmed and hyperphosphatemia ensues." (PMID 39399492, 2024). "In an effort to counterbalance hyperphosphatemia, serum levels of FGF23 and PTH rise and 1,25D levels are reduced, which are hallmarks for CKD." (PMID 38791164, 2024). "A response of systemic endocrine factors (i.e., parathyroid hormone (PTH) and fibroblast growth factor 23 (FGF23)) counterbalances renal phosphate retention and delays hyperphosphatemia at earlier CKD stages." (PMID 37108433, 2023). "Despite these points, we observed several comorbidities among our HD population such as anemia, hyperphosphatemia, low ALB, and elevated PTH." (PMID 37363538, 2023). "Excess phosphorus exerts toxic effects through a variety of pathways, including direct effects of hyperphosphatemia and indirect effects related to compensatory responses, such as increased FGF23 and PTH levels." (PMID 36904234, 2023). "Unlike other studies, our experimental approach allowed assessing a bone response to CKD before the development of hyperphosphatemia and systemic elevation of conventional phosphate regulatory factors, FGF23 and PTH." (PMID 37108433, 2023). "In conditions of hyperphosphataemia, FGF23 produced by osteoblasts and osteocytes in response to PTH increases renal phosphate excretion by down-regulating the expression of NaPi-IIa and NaPiIIc cotransporters in the proximal tubules." (PMID 36260560, 2022). "A high Pi load induces expression and secretion of the phosphaturic hormones parathyroid hormone (PTH) and fibroblast growth factor 23 (FGF23) that enhance urinary Pi excretion and prevent the onset of hyperphosphatemia." (PMID 35428804, 2022). "Three hormones, 1,25(OH)2D3, PTH, and FGF23 negatively regulate phosphate homeostasis and delays the occurrence of hyperphosphatemia." (PMID 35622784, 2022).
hyperphosphatemia (continued). "Hyperphosphatemia in BKO mice increased serum erythropoietin, FGF23, and PTH levels, nominating these factors as candidate mediators of bone loss in thalassemic mice with CKD during phosphate retention." (PMID 35622784, 2022). "The main limitation was the impossibility of disentangling the effect of hyperphosphatemia from other CKD-MBD-related abnormalities, such as the elevation of PTH and FGF-23." (PMID 34357974, 2021). "The delayed onset of hyperphosphatemia is probably due to the anti-regulatory effects of FGF-23 and PTH." (PMID 32823917, 2020). "By mating αKlothoflox/flox mice with these mice, they found mild hyperphosphatemia, modestly elevated serum FGF23 levels, decreased serum levels of PTH, and the abundant expression of the sodium-phosphate co-transporter NPT2A at the brush border membrane." (PMID 29720668, 2018). "In the first stages of CKD the phosphorus homeostasis (especially the phosphate concentration in plasma) is maintained by PTH and FGF23, but when GFR continues to fall (GFR < 50 mL/min) compensatory mechanisms fail leading to hyperphosphatemia." (PMID 29393923, 2018). "As well as the known acute effects of OSP (hyperphosphatemia, hypocalcemia and APN), the effects of OSP on serum PTH and FGF-23 levels and on the expression of NaPi co-transporter proteins in the kidney (NaPi-2a) were investigated." (PMID 25790436, 2015). "As CKD progresses, the compensation of elevations in PTH and fibroblast growth factor-23 (FGF-23) and decreased levels of 1,25(OH)2D3 becomes inadequate and inappropriate, resulting in hyperphosphatemia, abnormal bone, and extraskeletal calcification." (PMID 24558316, 2014). "As CKD progresses, compensation for the elevations of PTH and FGF-23 as well as the decreased levels of 1,25(OH)2D3 becomes inadequate, resulting in hyperphosphatemia, hypocalcemia, abnormal bone disorders, and extra-skeletal calcification." (PMID 24587915, 2014). "Most patients develop hyperphosphatemia only at CKD stages 4 and 5, despite the progressive elevation of serum PTH and FGF23 levels as a defense mechanism to prevent an increase in serum phosphate levels." (PMID 23339433, 2013). "Hyperphosphatemia inhibits 1α-hydroxylation of vitamin D and stimulates FGF23 and PTH production and parathyroid hyperplasia." (PMID 23760058, 2013). "In the course of CKD, PTH and FGF-23 levels become elevated prior to the development of hyperphosphatemia." (PMID 23324569, 2013). "The conversion to active vitamin D (1,25[OH]2D) is highly regulated, promoted by PTH and inhibited by FGF23 and hyperphosphatemia." (PMID 23760058, 2013). "After tPTX, the PTH level of SHPT patients is significantly reduced, which reduces the absorption of phosphate in the intestine and the release of phosphate from the bone, so that hyperphosphatemia can be significantly relieved." (PMID 40510469, 2025). "A series of in vivo and in vitro experiments have demonstrated that PTH contributes to vascular calcification through mechanisms independent of hyperphosphatemia." (PMID 41166265, 2025). "In animals with high PTH levels, the efficacy of anti-sclerostin antibody was compromised, likely due to PTH suppressing SOST (sclerostin gene) expression, interference with Wnt receptor, or the effects of hyperphosphatemia and increased FGF23." (PMID 38496297, 2024). "The health impact of an increase in FGF23 without CKD, hyperphosphatemia and elevated PTH is unclear." (PMID 38770543, 2024). "Our hypothesis for this left-shift in the PTH-Ca2+ curve is that the hyperphosphataemia of CKD will promote the direct binding of PO4 to the CaR stabilising its inactive conformation and thus permitting increased PTH secretion." (PMID 37064904, 2023).
hyperphosphatemia (continued). "The excretory capacity of the kidney for phosphorus is limited at relatively early stages of CKD despite the hormonal compensation of parathyroid hormone (PTH) and fibroblast growth factor 23 (FGF23), contributing to the elevation of serum phosphorus level (i.e., hyperphosphatemia)." (PMID 37242150, 2023). "Both hormones increase as kidney function declines, presumably as a response to maintain normal phosphate balance, but when patients reach kidney failure, PTH and FGF23 fail to exert their phosphaturic effects, leading to hyperphosphatemia and further elevations in PTH and FGF23." (PMID 36977891, 2023). "Notably, bone alterations in these models occurred against the background of hyperphosphatemia and significant changes in the circulating levels of FGF23, PTH, Dickkopf-1, and sclerostin." (PMID 37108433, 2023). "Thus, Tmem174, a strongly correlated molecule with NaPi2a in the GCNs, is thought to be involved in the regulation of NaPi2a by PTH and FGF23 in the kidney and the prevention of hyperphosphatemia in response to a high dietary Pi load." (PMID 35428804, 2022). "Thus, the relative contribution to the cardiovascular disease burden of progressive CKD per se, hyperphosphatemia, increased FGF-23 and decreased αKlotho levels, and changes in PTH and 1,25(OH)2D need detailed clarification." (PMID 35511366, 2022). "Ultimately, high dietary Pi as well as PTH and FGF23 (both hormones produced in states of hyperphosphatemia or upon ingestion of Pi-rich diets) reduce renal reabsorption of Pi by downregulating the expression of cotransporters, whereas low dietary Pi triggers the opposite effects." (PMID 36074191, 2022). "Therefore, PTH and FGF‐23 exert their harmonious effects in the regulation of plasma Ca2+ levels by preventing hyperphosphatemia and hypermagnesemia." (PMID 35385223, 2022). "In renal tubules, PTH and FGF‐23 down‐regulate the Na2+‐dependent Pi cotransporters, (NaPi)‐IIa and NaPi‐IIc, and increase urinary Pi excretion to prevent hyperphosphatemia." (PMID 35385223, 2022). "Male C57BL/6 mice maintained for 14 months on CPD in our study demonstrated an increase in systolic, mean arterial, and pulse pressure, independent of hyperphosphatemia or increased intact PTH." (PMID 36289771, 2022). "Recently, it has been shown that hyperphosphatemia inhibits the CaSR in a noncompetitive manner and thus stimulates PTH secretion which in turn increases renal excretion of Pi." (PMID 34068220, 2021). "No clinically relevant changes in serum calcium, urinary calcium, or intact parathyroid hormone were observed throughout this study, and no clinically significant evidence of hyperphosphatemia or ectopic renal calcification by ultrasound was observed." (PMID 32967046, 2021). "It is therefore possible that the observed link between hyperphosphataemia and renal interstitial fibrosis may be attributable to some other mechanism, such as resultant increases in the phosphaturic hormones FGF-23 and PTH." (PMID 33375963, 2021). "Compared with Klotho+/+ (WT) mice, KLKO mice exhibited high plasma concentrations of FGF23 and 1,25(OH)2D3, hyperphosphatemia, and hypercalciuria, but not ionized Ca or PTH." (PMID 32026654, 2020). "Specifically, by increasing extracellular Pi, at concentrations observed in CKD, we demonstrate that hyperphosphatemia inhibits the CaSR in a noncompetitive manner and thus increases PTH secretion." (PMID 31619668, 2019). "When modulating vitamin D status, one should consider the use of vitamin D analogues, such as paricalcitol, which inhibit PTH synthesis, without substantially inducing hyperphosphatemia, providing promising therapies for restoration of vitamin D levels." (PMID 31551803, 2019). "Furthermore, hyperphosphataemia is related to progression of CKD, because it stimulates parathyroid hormone secretion and consequently secondary renal hyperparathyroidism (SRHP), which increases nephron loss." (PMID 31273944, 2019).
hyperphosphatemia (continued). "Low calcium and hyperphosphatemia further exacerbate SHPT and elevate PTH and FGF23 levels." (PMID 30159331, 2018). "Moreover, hyperphosphatemia also stimulates FGF23 secretion, resulting in an increased renal P excretion, a reduced intestinal P absorption and decreased plasma PTH and calcitriol concentrations." (PMID 26870965, 2016). "One might speculate that in addition to PTH resistance, decreased klotho expression from low 1,25(OH)2D3 concentrations could hamper FGF-23 receptor signaling, resulting in hyperphosphatemia and elevated PTH secretion." (PMID 26046642, 2015). "As CKD progresses, the ability to compensate for elevations in parathyroid hormone (PTH) and fibroblast growth factor-23 and for decreases in 1,25(OH)2D3 becomes inadequate, which results in hyperphosphatemia, abnormal bone disorders, and extra-skeletal calcification." (PMID 24587915, 2014). "As CKD progresses, compensation for the elevations in parathyroid hormone (PTH) and fibroblast growth factor-23 (FGF-23) and for reduced levels of 1,25(OH)2D3 becomes inadequate, resulting in hyperphosphatemia, abnormal bone disorders, and extra-skeletal calcification." (PMID 24587915, 2014). "Possible mechanisms include fluctuations in calcium levels, hyperphosphatemia, and a lack of PTH." (PMID 40294163, 2025). "Therefore, serum phosphate levels are recommended to be maintained within the reference range (2.5 to 4.5 mg/dL) among other laboratory examinations such as serum calcium and parathyroid hormone levels for the treatment of mineral and bone disorder (MBD) and hyperphosphatemia in CKD." (PMID 36827665, 2023). "In addition, CaSR has been observed as a phosphate receptor in the parathyroid gland, and hyperphosphatemia, as a non-competitive inhibitor, inhibits its activity, thereby enhancing PTH production." (PMID 36267284, 2022). "In summary, although the data are not totally consistent, chronic ingestion of a high phosphate diet over prolonged periods may induce hyperphosphatemia both in human subjects and mice with normal renal function, despite increases in FGF23 and PTH and a decrease in calcitriol in the blood." (PMID 35511366, 2022). "The lack of PTH also leads to hyperphosphatemia because the phosphaturic actions of PTH are lost." (PMID 35036185, 2021). "In addition, lanthanum carbonate, in RCT of CKD stage 3b/4 patients without hyperphosphatemia, did not significantly affect on arterial stiffness, aortic calcification, and serum phosphorus, PTH, and FGF23 levels for 96 weeks." (PMID 34069053, 2021). "However, in our model, it was not possible to identify whether this occurred as a direct effect of phosphate overload or because of abnormalities in PTH and FGF-23 levels, induced by hyperphosphatemia." (PMID 34357974, 2021). "As the effect of hyperphosphatemia on the progression of CKD was not influenced by PTH replacement in an experimental model, we wonder whether phosphate would have a direct role on kidney Smad signaling." (PMID 34357974, 2021). "We do not doubt that hyperphosphatemia increases PTH synthesis in CKD." (PMID 28445401, 2017). "However, phosphaturic factors such as fibrobast growth factor 23 (FGF23) or parathyroid hormone (PTH) are significantly increased at earlier stage of CKD and may compensate for a positive phosphate balance and prevent from hyperphosphatemia." (PMID 25032144, 2014). "Despite the presence of phosphate retention in this early period, hyperphosphatemia does not develop until later stages owing to an increase in parathyroid hormone (PTH) and fibroblast growth factor 23 (FGF-23) whose actions result in augmented urinary phosphate excretion." (PMID 23324569, 2013). "Serum FGF-23 levels have been reported to increase in the very early stages of CKD, and the increase may represent a long-term, delayed response to transient episodes of hyperphosphatemia occurring in the early stage of CKD, possibly when the rapid response of PTH is becoming insufficient." (PMID 21234310, 2010).
hyperphosphatemia (continued). "Interestingly, it has been recently shown that phosphate might have an inhibitory effect on the CaSR independent of calcium, thereby providing a mechanism for PTH secretion in response to hyperphosphatemia." (PMID 36246903, 2022). "Indeed, recent studies in uremic rats comparing the impact of elevated and normal PTH levels (achieved through parathyroidectomy and PTH 1-34 supplementation), demonstrated for the first time an effect of high PTH on VC independent of hyperphosphatemia, which was corroborated in vitro." (PMID 34836090, 2021). "The Kidney Disease: Improving Global Outcomes (K/DIGO) guidelines mention that early CKD metabolic status may involve intermittent hyperphosphatemia, mild increases in PTH, or other bone turnover marker changes without altered bone strength or fragility fractures." (PMID 24501586, 2013). "In the kidney, phosphate reabsorption depends on parathyroid hormone (PTH), fibroblast growth factor 23 (FGF23) and dietary phosphate, but in CKD patients, hyperphosphatemia is a complication independent of PTH and calcitriol levels." (PMID 35203651, 2022). "Although SIK inhibition is not involved in PTH-mediated phosphaturia, indirectly, SIK inhibition might even correct hyperphosphatemia in hypoparathyroidism, which is a consequence of absent PTH and inappropriately low FGF23." (PMID 37115697, 2023). "Although hyperphosphatemia increases fibroblast growth factor 23 (FGF23, a hormone that inhibits the action of NaP2a and NaP2c, decreasing renal tubular resorption of phosphorus), this increase is not enough to compensate for the lack of PTH." (PMID 36382754, 2022).